STAT3 (signal transducer and activator of transcription 3)
Diseases named in the same sentence as STAT3 in open-access papers (continued):
Sharing a sentence is not in itself a finding about the gene and the disease.
tumor (continued). "STAT3, activated by phosphorylation, is considered as mediator of tumorigenesis because of its role in promoting cellular proliferation, resistance to apoptosis, tumor angiogenesis, invasion, and migration of cancer cells." (PMID 26888313, 2016). "Moreover, AONs have been used to switch STAT3 isoforms in cancer cells to promote apoptosis and inhibit tumor growth." (PMID 26909609, 2016). "Aberrant STAT3 signaling has been implicated in carcinogenesis: STAT3 is constitutively activated in cells transformed by diverse oncoproteins or tumor viruses, and elevated STAT3 signaling prevents apoptosis and confers survival advantages like chemo-resistance or radio-resistance." (PMID 27259262, 2016). "Our study may provide a mechanistic reason such that inhibition of STAT3 may reverse the epigenome and thus restoring the expression of tumor suppressor genes." (PMID 27528092, 2016). "Moreover, Phesse and co-workers have observed that partial suppression of JAK/STAT3 signaling in APC-mutant mice is sufficient to diminish tumor growth by reducing Bmi-1 dependent repression of p21 and p16." (PMID 27489351, 2016). "Recent studies have suggested that curcumin could inhibit STAT3 phosphorylation, cell proliferation, tumor sphere formation in colon CSCs." (PMID 27338343, 2016). "STAT3 is involved in the regulation of myeloid cells toward a more suppressive phenotype and since the myeloid population was affected by gemcitabine the level of phosphorylated STAT3 was evaluated in tumor cells and monocytes in vitro in response to gemcitabine." (PMID 27687804, 2016). "In both the B16 melanoma and MB49 bladder carcinoma murine tumor models, IL-17 produced by CD4+ T cells activated STAT3 in both tumor and stromal cells, leading to the expression of both anti-apoptotic and pro-angiogenic proteins within the tumor microenvironment." (PMID 27589814, 2016). "To investigate this, we performed biochemical analysis of xenograft lysates, which confirmed RAF1 knockdown and recapitulated the increased expression of YAP1 and GP130 as well as the higher levels of STAT3 phosphorylation observed in the autochthonous tumours." (PMID 28000790, 2016). "The expression of activated STAT3 was related to tumor invasion and poor prognosis of CRC." (PMID 27756247, 2016). "STAT3 is also thought to be an important mediator of tumor immune suppression." (PMID 27833081, 2016). "In addition, Fascin expression in tumor tissues from S3I-201 treated mice was also inhibited, suggesting the control of Fascin by STAT3 in vivo." (PMID 25992623, 2015). "Moreover, myeloid HO-1-induced expressions of VEGF and IL-10 promoted tumor cell extravasation and STAT3 activation, which are crucial for the survival and successful colonization of tumor cells in metastatic sites." (PMID 25885228, 2015). "Briefly, we confirm combinational STAT3 inhibition by S3I-201 may significantly reduce tumor growth by reducing HNSCC CSCs population in vitro and in vivo." (PMID 26556875, 2015). "Indeed, several reports correlate high levels of tumor-secreted cytokines, such as IL-6 and IL-10, with STAT3-mediated activation of anti-apoptotic factors and drug resistance." (PMID 26106584, 2015). "In addition, pSTAT3 expression was detected in 48 % of feline OSCC tumor samples, further supporting STAT3 as a potential therapeutic target in this disease." (PMID 26272737, 2015). "Therefore, prolonged inhibition of Src and Stat3 signaling by combining dasatinib and CYT387 is associated with enhanced inhibition of tumor growth with good tolerability." (PMID 26625308, 2015). "These make us speculate that miR-124 might function as a potential tumor suppressor in esophageal caner, and STAT3 signaling pathway might be involved in the suppressive effects." (PMID 25928665, 2015).
tumor (continued). "Interestingly, this previously unrecognized finding in cancer cells, highlighted a new potential oncogenic network that led us to investigate STAT3 activity status in our tumor samples correlating them to CB1 expression levels." (PMID 26008966, 2015). "We investigated whether BSN either alone or in combination with paclitaxel can affect STAT3 activation in NSCLC tumor tissues." (PMID 25788267, 2015). "In tumor cells, contrastively, tanshinone-1 could not only make phosphorylation of Stat3 at Tyr705 disappear but also reduce the hypoxia-induced accumulation of HIF-1α to its baseline levels at normoxia." (PMID 26202747, 2015). "To determine whether STAT3 pathway activity is required for the survival or self-renew of tumor cells, we used S3I-201, a novel inhibitor of STAT3 by blocking dimerization for in vitro functional experiment." (PMID 26556875, 2015). "Notably, cisplatin showed a synergistic effect with STAT3 knockdown to significantly reduce tumor volumes in the transplanted mice." (PMID 25638155, 2015). "Therefore, RKIP downregulation promotes tumor invasion and metastasis possibly through activating Stat3 signaling, but it needs to be validated." (PMID 25915430, 2015). "Tumor-promoting cytokines released by immune/inflammatory cells, including IL-6, act in a paracrine manner to activate transcription factors, such as NF-κB, STAT3 and AP-1, to achieve their effects in many types of cancer cells." (PMID 25504436, 2015). "Interestingly, a strict and unexplored directionality CB1→STAT3 was found both in almost all tumor tissues (18/23) and in patients primary cell lines where the levels of active STAT3 expression followed those of CB1." (PMID 26008966, 2015). "In addition, tumor-infiltrating MDSCs produce pro-angiogenic factors, such as VEGF, in a STAT3-dependent manner and stimulate tumor angiogenesis." (PMID 26317647, 2015). "Indeed, we found that p-STAT3 expression is critical for maintaining stemloid cancer cell properties, including tumor initiation and resistance to chemotherapeutics in HNSCC." (PMID 26556875, 2015). "Additionally, tumor volume and weight are significantly inhibited through the suppression of Akt, mTOR, and Stat3, accompanied by a decrease in the expression of MMP-2 and MMP-9 in vivo." (PMID 26202311, 2015). "In addition, STAT3 inhibition has been shown to suppress tumor growth and enhance the sensitivity to drugs in a variety of solid tumors." (PMID 28031890, 2015). "Given the broad alteration of the STAT3 and NFkB signaling pathways in cancer and the presence of ALDHbright cells in many neoplastic diseases, the conclusion of this study may be of broader relevance." (PMID 25868979, 2015). "Thus, targeting STAT3 activation is essential for overcoming tumor resistance to chemotherapy and radiotherapy." (PMID 25605256, 2015). "In addition to modulating PCC-autonomous actions, and cancer-associated inflammatory signaling, our findings suggest that STAT3 acts in ECs to promote tumor angiogenesis, and facilitate angiocrine actions." (PMID 25762644, 2015). "Chronic infection may lead to constitutive induction of COX-2 expression, which promotes the synthesis of PGE2 to enhance STAT3 phosphorylation and the regulation of tumor growth." (PMID 26231035, 2015). "In TSU cells, phosphorylation of STAT3 (via JAK) is required for tumor growth." (PMID 25785244, 2015). "STAT3 and NF-κB could be activated by IL-6 to prevent apoptosis and promote proliferation of malignant tumor cells." (PMID 25934640, 2015). "We could further detect a tendency of FOXM1 and STAT3 to be higher expressed in the metastasis group of tumor tissue than in the primary tumor group." (PMID 25797272, 2015). "Our discoveries suggest that the miR-197/CKS1B/STAT3-mediated network can drive tumor PD-L1 expression as a biomarker of this cascade, and miR-197 replacement therapy may be a potential treatment strategy for chemoresistant NSCLC." (PMID 25597412, 2015).
tumor (continued). "Overall, the impairment of STAT3 activation can inhibit tumor growth and metastasis." (PMID 25915156, 2015). "Because IL-17 can promote tumor growth through the STAT3 signaling pathway, we investigated whether STAT3 is involved in IL-17-mediated MDA-MB231 cell proliferation." (PMID 25992978, 2015). "Inflammatory cells in the tumor microenvironment may release cytokines to directly stimulate oncogenic signaling in cancer cells, including NF-κB, STAT3 and HIF1α signalings, resultantly promoting cancer survival and proliferation." (PMID 25504436, 2015). "These preliminary results therefore indicate that SR141716 might really have dual combined activity on tumor growth and immunogenicity by a mechanism that can involve STAT3." (PMID 26008966, 2015). "STAT3 may, therefore, represent a promising target to boost anti-tumor function of TIL, but must be thoroughly investigated in proposed therapeutic platforms." (PMID 26393659, 2015). "To investigate whether HPV infection would play a role in orchestrating a tumor environment with heightened active Stat3 and IL-17 levels, we conducted bivariate correlational analyses." (PMID 25706309, 2015). "STAT3 is a critical mediator of the pro-angiogenic and immunosuppressive activities of myeloid cells in the tumor microenvironment, and it can lead to enhanced cell cycle progression and neovascularization, thus promoting tumor growth." (PMID 25999952, 2015). "Numerous studies have shown that STAT3 inhibitors lead to human tumor regression in animal models." (PMID 25331984, 2015). "Moreover, stat-3 expression in the tumor cells promotes tumor immune evasion by inhibiting pro-inflammatory cytokine signaling and by amplifying Tregs." (PMID 26137448, 2015). "Hence an advantage of targeting STAT3 in GBM is that the inhibition of this pathway affects multiple downstream molecules in the GSC tumor compartment which drives GBM and is invasive." (PMID 26283544, 2015). "However, abundant evidence indicates that STAT3 is persistently activated in several cancers, with a crucial position in tumor onset and progression." (PMID 26631279, 2015). "According to bioinformatics data, we hypothesized that the STAT3/Snail axis positively regulates cancer stem-like properties and tumor-initiating capabilities in ATRT." (PMID 25638155, 2015). "Zhou showed that STAT3 could induce PTTG expression to facilitate tumor growth and metastasis of CRC." (PMID 25947346, 2015). "In addition, neutrophil-derived reactive oxygen species further decrease the adhesion-promoting properties of the extracellular matrix and, via activation of nuclear factor (NF)-kB and STAT3, inhibit apoptosis of the tumour cells." (PMID 25889889, 2015). "Western blots of the tumor tissues retrieved from the mice at the end of the experiments revealed that tocilizumab, but not paclitaxel, inhibited the main downstream effector of IL-6 signaling, i.e. phosphorylated STAT3." (PMID 26287605, 2015). "STAT3 activity is required for melanomagenesis and increases tumor invasiveness." (PMID 26116372, 2015). "Moreover, the combined treatment of TG101348 and erlotinib induced apoptosis, inhibited the activation of p-EGFR and p-STAT3, and inhibited tumor growth of erlotinib-resistant NSCLC cells in vivo." (PMID 25869210, 2015). "HER2 acts as a STAT3 co-activator for cyclin D1 promoter activation to promote tumor proliferation." (PMID 25674538, 2015). "In addition, treatment with EEHDW appeared to inhibit CRC growth in vivo via the inhibition of the STAT3 signaling pathway and suppress tumor angiogenesis via the hedgehog signaling pathway." (PMID 25789077, 2015).
tumor (continued). "Inhibition of EGFR could effectively increase anti-tumor activity of agents targeting other signaling pathways, such as STAT3 or AKT." (PMID 25928246, 2015). "Among the Stats, Stat3 is the most widely related with tumor development." (PMID 26169986, 2015). "Consistent with these previous reports, our study found that cisplatin can cause “oncogenic-type” of drug resistance which simultaneously activates STAT3/Snail pathway to make cell aggressive, such as tumor invasion and cancer stem-like capability in ATRT-CisR cells." (PMID 25638155, 2015). "STAT3 has been documented to be involved in tumor growth and metastasis in many types of tumor." (PMID 26528698, 2015). "Knockdown of STAT3 in xenografted human AC cells increases tumour growth." (PMID 25734337, 2015). "All of these studies evaluated the expression of p-STAT3 in tumor samples by IHC." (PMID 26024373, 2015). "Understanding of STAT3 functions is helpful in identifying a potential target for tumor treatment." (PMID 25923701, 2015). "The activation of STAT3 pathway, mainly due to the effect of tumor-released factors, plays indeed a critical role in cell survival and chemo-resistance of MM as well as several other tumor cells." (PMID 26338963, 2015). "In summary, our study discovered a natural small molecule inhibitor of STAT3, EB, which specifically and covalently binds to Cys712 of STAT3 to inhibit its phosphorylation and activation and induces apoptosis of tumor cells, especially those whose survival and growth are dependent on STAT3." (PMID 26010889, 2015). "Inflammation in the tumor microenvironment induces STAT3 activation within tumors and Tregs." (PMID 26167500, 2015). "STAT3 signaling has also been widely implicated in tumor progression and tumor cell stemness, not least through induction of HIF-1α and Notch1." (PMID 26343197, 2015). "Restoring miR-124 function could represent an alternative approach to reduce therapeutically STAT3 expression, thereby attenuating aggressive tumor properties." (PMID 25928665, 2015). "Recently, STAT3 has been indicated as a key element in driving the immunosuppressive, pro-angiogenic, pro-tissue reconstruction, and pro-survival microenvironment that is characteristic of many tumours." (PMID 26635904, 2015). "Together, these results implicate that STAT3 ablation results in a considerably different tumour microenvironment composed of more myeloid cells, increased CD4+/CD8+ lymphocyte ratio and enhanced angiogenesis in our murine as well as in the human AC xenograft models." (PMID 25734337, 2015). "STAT3 is both overexpressed and activated primarily as a function of autocrine secretion of IL-6/IL-10 by tumor cells, a survival mechanism that can be promoted in the context of mutations that drive NF-κB activation and subsequent NF-κB-mediated cytokine expression." (PMID 26575169, 2015). "Inhibition of STAT3, like repression of NF-kB, may be a common pathway involved in the tumour suppressive action of many phytochemicals." (PMID 26635904, 2015). "Interestingly, we found a significant decrease in STAT3 expression levels in KRAS mutant human tumours compared with lung tumours with wild-type KRAS in the first cohort of smoking patients." (PMID 25734337, 2015). "Importantly, many activated oncogenes including vSRC and RAS require STAT3 to elicit tumor transformation." (PMID 26106584, 2015). "We recently reported that gankyrin could promote CCA tumor growth and metastasis through activation of IL-6/STAT3 signaling." (PMID 26015398, 2015). "Importantly, elevated levels of STAT3 phosphorylation were correlated with tumor invasion, metastasis, and worse prognosis in colorectal, hepatocellular and other carcinoma." (PMID 26417930, 2015). "Whether activated by cytokines such as IL-6, stressors like reactive oxygen species or driven by the progression towards castration resistance, STAT3 activation plays a vital role in the self-renewal and tumor-propagating capacity of PCSCs." (PMID 25595909, 2015).
tumor (continued). "Interestingly, EGFR-independent phosphorylation of STAT3 has been identified as a mechanism of tumor resistance to agents targeting SFK." (PMID 25779657, 2015). "Moreover, formononetin inhibited the expression of TGF-β, CD31, COX-2 and Ang2 downstream-regulator of STAT3, which stimulates tumor angiogenesis and tumor growth." (PMID 26575424, 2015). "Furthermore, Icaritin-treated hepatospheres lost tumor initiating capability and the IL-6Rs/Jak2/Stat3 axis of hepatospheres treated with Icaritin was also suppressed." (PMID 26376676, 2015). "As disruption of energy metabolism is a common feature of all tumor cells, this central metabolic role of both Y-P and S-P STAT3 may well explain the addiction to STAT3 shown by so many biologically distinct tumors." (PMID 26106584, 2015). "GSEA further showed that our murine Stat3-deficient KrasG12D tumours strongly correlate with a gene expression signature associated with human KRAS mutant lung tumours, and importantly, also with a poor prognosis-gene signature—more than Stat3-proficient KrasG12D tumours." (PMID 25734337, 2015). "Exosomes derived from mouse tumor cells could enhance the suppressive activity of MDSCs via the STAT3 pathways." (PMID 26556857, 2015). "But the activation of STAT3 is persistent in the tumor tissues and cells." (PMID 26788112, 2015). "In fact, in the absence of IL-1RT1 signaling gastric pathology develops more rapidly and extensively in both the antrum and gastric cardia suggesting that IL-1RT1 signaling may minimize tumor burden by antagonizing IL-11/STAT3 mediated pathology." (PMID 25528766, 2015). "In addition, immunoblotting of tumor tissue showed that high STAT3 activity in Ad-GSC xenografts was evident by virtue of Y705-STAT3 phosphorylation, and that WP1066 treatment of mice nearly abolished STAT3 activity." (PMID 25955030, 2015). "Clinical trials are warranted to assess whether therapeutic strategies targeting STAT3 or IGF-2 would circumvent tumour angiogenesis and pro-invasive consequences, overcoming innate resistance to anti-IGF-1R monoclonal antibody-based therapies." (PMID 26465273, 2015). "Moreover AG490 is able to revert immunosuppression caused by tumor-released factors or induced by tumor viruses such as KSHV, which correlates with STAT3 activation in immune cells." (PMID 25695042, 2015). "In contrast, STAT3 is required to maintain constitutive NF-κB RelA activity in tumor cells." (PMID 26299368, 2015). "One of the main transcriptional activators of VEGF expression in hypoxic tumor lesions is STAT3." (PMID 26317647, 2015). "STAT3 has been identified as a novel tumor target and several inhibitors are under development." (PMID 25460504, 2015). "Interestingly, MMP-1 expression correlates with tumor high grade and invasiveness, thus suggesting that STAT3 activation is directly related to malignant behavior of T24 BC cells." (PMID 28031890, 2015). "STAT3 activity supports tumour-cell survival by up regulating expression of the anti-apoptotic protein BCL-XL (B-cell lymphoma-2-like) and many other proteins involved in cell proliferation and survival including myeloid cell leukaemia 1 (MCL1), cyclin D1 and MYCC." (PMID 26186918, 2015). "Last, our observations might likely be of interest for other neoplastic diseases characterized by STAT3-NFkB activation and chemoresistance." (PMID 25868979, 2015). "Furthermore, the inhibition of STAT3 signaling using small-molecule inhibitor Stattic has been shown to target both tumor-initiating cells (TICs) and differentiated cells." (PMID 28031890, 2015). "Others have targeted STAT-3 in human tumor models using various techniques." (PMID 26458879, 2015). "The epigenetic silencing of SHP-1 results in loss of its tumor suppressor function and re-expression of SHP-1 by 5-Aza may enhance sensitivity to CEP-701 through inactivation of STAT3." (PMID 26547689, 2015). "Among them, STAT3 plays a prominent role in tumor growth and invasion." (PMID 28031890, 2015).